ERCC3 (ERCC excision repair 3, TFIIH core complex helicase subunit)
Diseases named in the same sentence as ERCC3 in open-access papers (continued):
Sharing a sentence is not in itself a finding about the gene and the disease.
pancreatic cancer (4 papers, 2020 to 2024). "Furthermore, from the TCGA dataset, we found that high expression of ERCC3 was associated with poor overall survival in pancreatic cancer patients." (PMID 33854616, 2021). "What's more, ERCC3 OE was associated with poor prognosis for pancreatic cancer patients." (PMID 33854616, 2021). "Most importantly, 91.7% (55/60) of pancreatic cancer specimens and 56.3% (31/55) of adjacent samples had high expression of ERCC3, and the staining score of ERCC3 in pancreatic cancer and associated-adjacent tissues was significantly different (p<0.05, χ2 test)." (PMID 33854616, 2021). "Besides, analysis of the dataset in The Cancer Genome Atlas (TCGA) revealed that high expression of ERCC3 was associated with poor overall survival in pancreatic cancer patients (p=0.0136)." (PMID 33854616, 2021). "The expression of ERCC3 in pancreatic cancer specimens and relevant cancer-adjacent normal pancreatic tissues were first investigated by IHC and evaluated by staining scores." (PMID 33854616, 2021). "Next, we examined the exact mechanism through which ERCC3 affected prognosis and outcomes in pancreatic cancer patients." (PMID 33854616, 2021). "Yet, detailed molecular mechanisms through which ERCC3 regulates the progression of pancreatic cancer need to be further elucidated." (PMID 33854616, 2021). "In this study, we examined the expression profile of ERCC3 in pancreatic cancer and its clinical significance." (PMID 33854616, 2021). "Next, we investigated the ERCC3 mRNA expression and clinical information of 177 pancreatic cancer cases extracted from TCGA." (PMID 33854616, 2021). "Our in vitro results showed that ERCC3 had a noticeable effect in promoting pancreatic cancer cells proliferation." (PMID 33854616, 2021). "In Cox regression analysis, ERCC3 was an independent prognostic factor for overall survival in pancreatic cancer (p<0.001)." (PMID 33854616, 2021). "This study aimed to investigate the expression and functions of ERCC3 in pancreatic cancer patients and its relation with clinicopathological features." (PMID 33854616, 2021). "Our immunohistochemical analysis showed that ERCC3 expression was notably increased in pancreatic cancer tissues and clinically relevant." (PMID 33854616, 2021). "In this study, the dataset of ERCC3 mRNA expression from The Cancer Genome Atlas (TCGA) was used to analyze the role of ERCC3 in pancreatic cancer and its clinicopathological significance." (PMID 33854616, 2021). "ERCC3 gene expression level was higher in pancreatic cancer specimens compared with normal pancreas tissues (p<0.05)." (PMID 33854616, 2021). "This study first demonstrated the correlation between ERCC3 expression and prognosis of pancreatic cancer patients." (PMID 33854616, 2021). "Overall, all these data indicated that ERCC3 overexpression (OE) might present a poor survival biomarker for pancreatic cancer patients." (PMID 33854616, 2021). "A series of experiments were performed to confirm whether ERCC3 could be used as a promising biomarker for improving the diagnosis and predicting prognosis in patients with pancreatic cancer." (PMID 33854616, 2021). "Besides, ERCC3 expression was increased in pancreatic cancer tissues and it was clinically relevant." (PMID 33854616, 2021). "Taken together, this study suggested that high expression of ERCC3 might be a poor prognostic factor in human pancreatic cancer and might be used as a promising therapeutic target for pancreatic cancer treatment." (PMID 33854616, 2021). "Furthermore, our in vitro data further suggested that the overexpression of ERCC3 significantly promoted pancreatic cancer (BxPC-3, CFPAC-1, and PANC-1 cells) proliferation, invasion, and migration." (PMID 33854616, 2021). "Additionally, a transwell assay was performed to evaluate the impact of ERCC3 expression on migration and invasion in pancreatic cancer cells." (PMID 33854616, 2021).
pancreatic cancer (continued). "In addition, ERCC3 could promote proliferation, invasion, and migration of pancreatic cancer cells in vitro." (PMID 33854616, 2021). "Furthermore, Cox regression was performed to analyze the dataset, and the results showed that ERCC3 could be considered as an independent prognostic factor for overall survival in pancreatic cancer, (p<0.001)." (PMID 33854616, 2021). "In addition, weak, moderate and strong positive expression levels of ERCC3 were detected in 8.3% (5/60), 30% (18/60), and 61.7% (37/60) of the pancreatic cancer tissues, and in 43.6% (24/55), 41.8% (23/55) and 14.5% (8/55) of the noncancerous pancreas tissues, respectively." (PMID 33854616, 2021). "Moreover, we found that the high expression of ERCC3 could be considered as an independent unfavorable prognostic biomarker for pancreatic cancer patients." (PMID 33854616, 2021). "Therefore, we supposed that ERCC3 overexpression might inhibit pancreatic cancer cells apoptosis when distant metastasis occurred." (PMID 33854616, 2021). "Furthermore, we discovered that ERCC3 could affect pancreatic cancer cell apoptosis." (PMID 33854616, 2021). "Yet, so far, no studies have examined the expression profile of ERCC3 in human pancreatic cancer, and the clinical significance of ERCC3 in human pancreatic cancer is still unknown." (PMID 33854616, 2021). "For example, AC068282.3 and ERCC3 were significantly co-expressed in both FANTOM5 samples and in TCGA pancreatic cancer (p < 0.05), but in response to Wnt inhibition, they were no longer co-expressed (p = 0.26)." (PMID 33092630, 2020).
bladder cancer (3 papers, 2016 to 2024). "However, so far there is no report on the expression level of ERCC3 (TFIIH p89) in bladder cancer." (PMID 27626805, 2016).
colon cancer (3 papers, 2018 to 2025). "For colon cancer, high ERCC3 expression was related to better T stage; ERCC5 expression indicated deeper T stage and distant metastasis; DDB2 expression suggested earlier TNM stage." (PMID 29568775, 2018). "For colon cancer, high ERCC3 expression was related to better T stage." (PMID 29568775, 2018).
leukemia (3 papers, 2017 to 2021). A malignant (clonal) hematologic disorder, involving hematopoietic stem cells and characterized by the presence of primitive or atypical myeloid or lymphoid cells in the bone marrow and the blood. "For example, AC068282.3 was linked to ERCC3 through 4 distinct ERCC3 eQTL SNPs that were also associated with leukemia by GWAS." (PMID 33092630, 2020). "Despite co-occurrence of leukemia-associated differentially expressed and mutated genes, gene set enrichment analyses identified one common gene set comprising downregulated genes expressed in fibroblasts with mutant forms of ERCC3 upon ultraviolet irradiation." (PMID 29221109, 2017).
hepatocellular carcinoma (2 papers, 2021 to 2023). A malignant tumor that arises from hepatocytes. "In contrast, dysregulation of ERCC3 (Excision repair cross-complementation group 3) levels has not been previously associated to EC, although different studies highlight the suppressor role of ERCC3 silencing in different cancers, as pancreatic or liver carcinomas." (PMID 36745330, 2023).
HIV-1 infection (2 papers, 2012 to 2020). The type species of lentivirus and the etiologic agent of acquired immunodeficiency syndrome (AIDS). "Notably, knockdown of a few DNA repair helicases including ERCC3 and RECQL4 diminishes HIV-1 infection, suggesting their role in viral DNA integration." (PMID 23020886, 2012).
melanoma (2 papers, 2013 to 2022). A malignant, usually aggressive tumor composed of atypical, neoplastic melanocytes. "The very significant overlap of transcripts differentially regulated in ERCC3 (XPB) deficient cells after UVR was the most striking of the gene sets overlapping with the transcripts altered in response to cisplatin in the melanoma cell lines." (PMID 23940574, 2013). "Thirdly, a higher ERCC3 expression could be associated with a better prognosis in melanoma, especially in younger patients." (PMID 35174087, 2022). "CXCL13 was suggested as a prognostic biomarker in melanoma before, but the correlation of ERCC3 with survival needs further validation." (PMID 35174087, 2022).
osteosarcoma (2 papers, 2024). A usually aggressive malignant bone-forming mesenchymal neoplasm, predominantly affecting adolescents and young adults. "Our main analysis identified significant associations with osteosarcoma for 12 variants in 8 genes: CTLA-4, ERCC3, IL-8, PRCKG, RECQL5, TNF-α, XRCC3, and VEGF." (PMID 38360742, 2024). "The pooled ORs of 12 variants in 8 genes (CTLA-4, ERCC3, IL-8, PRCKG, RECQL5, TNF-α, XRCC3, and VEGF) were significantly associated with the risk of osteosarcoma in the main analysis." (PMID 38360742, 2024).
pancreatic ductal adenocarcinoma (2 papers, 2019 to 2021). An infiltrating adenocarcinoma that arises from the epithelial cells of the pancreas. "For example, CR cells were established from PDX models with pancreatic ductal adenocarcinoma cells, a novel potential therapeutic target, ERCC3-Myc interaction, and a covalent inhibitor of ERCC3, triptolide, have been identified from CR cells." (PMID 31717887, 2019). "The CR technique was used for the first time to determine the important role of the MYC-ERCC3 interaction in pancreatic ductal adenocarcinoma (PDAC), and triptolide (a covalent ERCC3 inhibitor) was found to be a potential treatment target in MYC-dependent PDAC." (PMID 34150763, 2021).
UV-sensitive syndrome (2 papers, 2016 to 2024). UV-sensitive syndrome is a condition that is characterized by sensitivity to the ultraviolet (UV) rays in sunlight. "Interestingly, our results also found ERCC2(XPD), ERCC3(XPB) or ERCC5(XPG) mutations in two cases of UV-sensitive syndrome and in two cases with mixed XP/CS phenotypes." (PMID 27004399, 2016).
acute promyelocytic leukemia (1 paper, 2017). An aggressive form of acute myeloid leukemia (AML), characterized by arrest of leukocyte differentiation at the promyelocyte stage, due to a specific chromosomal translocation t(15;17) in myeloid cells. "In this study, we performed the expression analysis in human acute promyelocytic leukemia cells (HL60) in the presence of hydroquinone (HQ), a key benzene toxic metabolite, and found that HQ can induce down-regulation of ERCC3 after 72 h treatment (data not shown)." (PMID 28813025, 2017).
Down syndrome (1 paper, 2016). "One is ERCC3 (aliase XPB), a gene with increased expression in Down syndrome which codes for an essential core subunit of the eukaryotic basal transcription factor complex TFIIH: defective TFIIH results, via TAF7, in thymocyte failure to reach DN4 stage." (PMID 26848775, 2016).
Hypertension (1 paper, 2023). The presence of chronic increased pressure in the systemic arterial system. "Spironolactone is an FDA-approved drug for treating hypertension and also possesses the ability to degrade the key TC-NER gene ERCC3." (PMID 37306526, 2023).
laryngeal carcinoma (1 paper, 2018). Carcinoma that arises from the laryngeal epithelium. "Polymorphisms in other NER genes including ERCC1, ERCC2, ERCC3, ERCC4, ERCC5, and XPA have also been reported to pose as an increased risk in Laryngeal Cancer." (PMID 30410671, 2018).
metaplastic breast carcinoma (1 paper, 2024). A group of invasive breast carcinomas characterized by the presence of an adenocarcinomatous component which is admixed with a dominant component that is composed of squamous cells, spindle cells, or mesenchymal cells. "ERCC3 amplifications and deep deletions primarily occurred in breast invasive cancer not otherwise specified (NOS) and metaplastic breast cancer, respectively." (PMID 39742368, 2024).
Xeroderma pigmentosum complementation group B (1 paper, 2016). Xeroderma pigmentosum complementation group B (XPB) is an extremely rare subtype of xeroderma pigmentosum (XP; see this term), a rare photodermatosis predisposing to skin cancers. "Variants in ERCC3 (MIM 133510) cause not only TTD2 (MIM 616390) but also xeroderma pigmentosum complementation group B (XPB; MIM 610651)." (PMID 26880286, 2016).
Xeroderma pigmentosum complementation group C (1 paper, 2025). "The genes XPC (xeroderma pigmentosum, complementation group C) and ERCC3 (XPB) are particularly relevant to NER in MM." (PMID 41155462, 2025).
cancer (32 papers, 2010 to 2026). A tumor composed of atypical neoplastic, often pleomorphic cells that invade other tissues. "Multiple multilocus inherited neoplasia alleles syndrome cases with ERCC3 truncating mutations were reported, which implied that ERCC3 variants also possibly play a role in modifying the cancer phenotype." (PMID 39742368, 2024). "Numerous likely pathogenic/pathogenic loss of function (LoF) germline variants were observed in ERCC3, with rs145201970 (n = 42) representing the second most observed LoF variant in this gene in cancer patients after rs34295337 (n = 70)." (PMID 39001544, 2024). "As ERCC3 could help increase the sensitivity of cancer to radiation therapy, loss of EZH2-repression of these ERCC3 targets in t-AML indicates an increased radiosensitivity." (PMID 26043758, 2015). "In our cohort, fourteen patients harbored a monoallelic P/LPV associated with recessive disorders (NTHL1, RECQL4, ERCC3, FANCA, and BLM) and one patient harbored PV in a low penetrance cancer gene (TYR)." (PMID 36132150, 2022). "Other cancer-related genes, such as COL7A1, PRKAR1A, ERCC3, and MTAP, had variants with a conflicting interpretation of pathogenicity or VUS, or they were not reported in ClinVar." (PMID 32443704, 2020). "Of those listed, ERCC3, FANCA and FANCM LoF variants are good candidates for further research as potential cancer-susceptibility mutations as the normal functions of their gene products are in DNA repair pathways." (PMID 26023681, 2015). "It is reasonable to suppose that the possibilities for the different results of apoptosis rate in Bxpc-3, PANC-1 and CFPAC-1 are the heterogeneous nature of cancer and different signaling cascades activated in different cells when ERCC3 is overexpressed in downstream." (PMID 33854616, 2021). "Excision repair cross-complementing 3 (ERCC3) is an important member of nucleotide excision repair (NER) that is overexpressed in some cancers and may be regarded as a poor prognostic factor." (PMID 33854616, 2021). "Three of the identified mutations showed cosegregation with cancer (CHEK2, ERCC3 and FANCM)." (PMID 28050010, 2017). "However, in the literature ERCC2 and ERCC3 have no dominant link with cancer, whereas polymorphisms in ERCC4 have been linked to cancer predisposition." (PMID 38872153, 2024). "At present, few studies have reported the prognosis capability of ERCC3 mRNA expression in malignant tumors, and there are no reports in GC." (PMID 30417012, 2018). "Additionally, we assessed the allele frequencies of the genes in the gnomAD non-cancer cohort (n = 134 187), which showed significant differences in BRCA1, BRCA2, CHEK2, MUTYH, MSH6, POLE, and ERCC3 genes in comparison to our non-HBOC groups." (PMID 39148954, 2024).
tumor (24 papers, 2005 to 2026). "By contrast, FANCM, MRE11A and ERCC3 tumours either remained heterozygous, or lost the variant allele." (PMID 39794353, 2025). "In esophageal cancer, miR-192 enhances cisplatin sensitivity by targeting ERCC3/4 and increases tumor cell susceptibility to cytotoxic T lymphocytes by targeting BCL-2." (PMID 40087755, 2025). "The results suggested that the expression of ERCC3 was associated with the tumor extent (p=0.035, Fisher exact test) instead of other clinicopathological features." (PMID 33854616, 2021). "The decreased ERCC3 expression in tumor tissues of patient with p.Y116X mutation was found by IHC." (PMID 39742368, 2024). "In addition, the expression of ERCC3 has shown to be associated with the tumor extent (p=0.035)." (PMID 33854616, 2021). "Analysis of ribonucleic acid sequencing data from the Cancer Genome Atlas and the Genotype-Tissue Expression by bc-GenExMiner v4.9 demonstrated a decrease in ERCC3 expression in tumor tissues compared to both tumor-adjacent and healthy tissues." (PMID 39742368, 2024). "The tumor tissues of patients S-1, S-2, S-3, and S-5 tend to present a slightly decreased ERCC3 expression." (PMID 39742368, 2024). "Diffuse and mild ERCC3 staining was observed in the tumor tissues of patient S-1, S-2, S-3, and S-5." (PMID 39742368, 2024). "Our data suggested that the protein expression level of ERCC3 was higher in tumor tissues than in adjacent tissues." (PMID 33854616, 2021). "However, one specific study identifies miR-192-5p as a tumor suppressor, reversing cisplatin resistance in gastric cancer cells by targeting ERCC3 and ERCC4." (PMID 40087755, 2025). "Variants in genes like CTLA-4, ERCC3, and TNF-α might impact immune regulation and inflammatory responses, crucial in tumor microenvironment dynamics." (PMID 38360742, 2024). "By IHC analysis, ERCC3 negative expression was identified in the tumor tissues of patients with p.Y116X mutation." (PMID 39742368, 2024). "IHC analysis indicated an obviously ERCC3 negative in the tumor tissues of the patient with p.Y116X mutation, while in tissues of patients with variants of uncertain significance, mild or moderate staining nucleus in >80% of cells was found." (PMID 39742368, 2024). "Furthermore, the levels of DNA repair proteins (HMGB1, LIG, and XRCC1) and DNA excision repair protein (ERCC-3, a tumor-preventing gene) were detected by western blotting." (PMID 35473479, 2022). "Tumor mutation burden (TMB) had weak positive correlations only with CD274 (p = 0.01342; R = 0.127), CXCL9 (p = 0.038; R = 0.1078), and also with the XP cluster 2 genes ERCC3 (p = 0.00196; R = 0.157) and ERCC2 (p = 0.027; R = 0.114)." (PMID 35174087, 2022). "The CCK-8 assay was used to explore the effect of ERCC3 on tumor cell growth." (PMID 33854616, 2021). "We focused on some important events, for example, pathways of oncogenesis by Met, EIF4 pathway, downregulation of SMAD2-SMAD3-SMAD4 transcriptional activity, EZH2 targets, stemness, well vs. poorly differentiated tumor, epithelial mesenchymal transition, UV response via ERCC3, and metastasis." (PMID 32754191, 2020). "In this module, Ercc3 and Cetn2 (centrin 2) were positively correlated with tumor size." (PMID 30327455, 2018). "Finally, we found 3 pathogenic/likely-pathogenic mutations in ERCC3, RECQL4 and TSC2 genes, encoding transcription factors and tumor suppressors." (PMID 28423363, 2017).
adenocarcinoma (1 paper, 2023). A common cancer characterized by the presence of malignant glandular cells.